INS (insulin)
Diseases named in the same sentence as INS in open-access papers (continued):
Sharing a sentence is not in itself a finding about the gene and the disease.
Obesity (continued). "A few clinical trials have shown that GLP1RAs administration improves pregnancy rate, menstrual frequency, obesity, excess of androgen and insulin levels in PCOS patients." (PMID 37940910, 2023). "Although this does not provide direct proof that ceramide accumulation alone is sufficient to attenuate insulin signal transmission, it indicates the insulin-sensitizing effects of limiting ceramide build-up in obesity." (PMID 35789435, 2022). "For example, studies in human participants with obesity revealed that one year of oral AGE restriction resulted in reduced insulin resistance compared to individuals consuming a regular AGE diet." (PMID 35562970, 2022). "The current pharmacological treatment of MS focuses on oral antidiabetic drugs, insulin drugs, hypertension drugs, statins/fibrates, and anti-obesity drugs." (PMID 36014355, 2022). "Whereas excessive NO (mostly iNOS derived) induced by certain pathological factors, including obesity and inflammation, results in β-cell dysfunction, insulin secretion impairment, and hyperglycemia as well as the development of adipose tissue IR." (PMID 36338341, 2022). "Our results suggest that AME:AVE (3:1) treatment modulates the insulin signaling pathway and suppresses the expression of adipogenesis and lipogenesis-related proteins, thereby resulting in anti-obesity effects." (PMID 35164174, 2022). "Insulin target organs, such as adipose tissue, skeletal muscle, and liver, are affected by obesity at the morphological, functional, and molecular levels." (PMID 36230963, 2022). "The pentose phosphatase pathway is a major regulator of cellular reduction–oxidation homoeostasis and biosynthesis and modulates obesity‐induced inflammation and insulin sensitivity." (PMID 36162824, 2022). "Pharmacological or experimental lowering of insulin levels indeed ameliorates obesity which indicates that the support of lipogenesis by insulin is obesogenic." (PMID 36575472, 2022). "The 6p11.2 distal deletion includes the SH2B1 gene involved in leptin and insulin signalling and has been shown to have a polymorphic effect on obesity." (PMID 35590413, 2022). "Short-term exercise in conjunction with diet interventions has great impacts on decreasing metabolic risks and fasting insulin levels in children with obesity." (PMID 35457507, 2022). "We found that mice deficient in LXN showed resistance against high-fat diet (HFD)-induced obesity, glucose tolerance, insulin tolerance and hepatic steatosis." (PMID 35210404, 2022). "The new drug, Setmelanotide, is an eight-amino acid cyclic peptide labeled as BIM-22493 or RM-493 that functions as an MC4R agonist to treat the monogenic causes of obesity caused by POMC deficiency by lowering food intake and restoring insulin sensitivity." (PMID 36012526, 2022). "In fact, in endometria from women with obesity and PCOS, increased levels of molecules related to the tumor necrosis factor-alpha (TNFα) signaling pathway, which is considered to be an obesity marker and negative regulator of insulin action, can be observed." (PMID 35409282, 2022). "Neither classic IL-6 nor trans-signalling do influence the outcome of diet-induced obesity, insulin sensitivity and glycaemic control." (PMID 36387898, 2022). "There is compelling evidence that circulating nutritional factors (lipids, glucose), hormones (insulin, insulin-like growth factor, leptin), and cytokines (interleukins, tumor necrosis factor), among others, connect obesity and cancer." (PMID 36074318, 2022). "Congruently, the inflammatory signaling inhibition prevents the development of obesity and restores insulin sensitivity." (PMID 35112705, 2022). "As a consequence, NLRP3−/− and iNOS−/− animals are protected from obesity-related insulin resistance, macrophage infiltration, and extracellular matrix (ECM) deposition and are enriched in metabolically healthy adipocytes compared with WT mice." (PMID 35543703, 2022).
Obesity (continued). "Dietary carbohydrate is the most potent inducer of insulin release, which substantially stimulates the synthesis, uptake, and storage of fat in adipose tissue; this underlies the hypothesis that high-carbohydrate diets induce accumulation of excess adiposity and obesity." (PMID 35538513, 2022). "The finding that trodusquemine determines an enhancement of insulin‐stimulated tyrosine phosphorylation of hypothalamic insulin receptor β in a mouse model of diet‐induced obesity proves that trodusquemine is able to cross the blood–brain barrier." (PMID 36421008, 2022). "Diet-induced obesity mouse models, such as high-fat diet (HFD) feeding in C57BL/6J mice, are a well-established approach to study obesity and obesity-related complications, including systemic and peripheral insulin resistance." (PMID 36158197, 2022). "In obesity, the insulin and leptin resistance occurring in immune cells can be traced to an increased SOCS1/3." (PMID 35406000, 2022). "IGF-1 has also been linked to carcinogenesis; however, in contrast to insulin, there is much debate surrounding circulating total IGF-1 levels and obesity in humans." (PMID 36038791, 2022). "We also observed some differences between overweight/obesity groups in terms of fasting insulin and HDL-cholesterol parameters." (PMID 35228658, 2022). "Obesity can also result in hyperinsulinemia, so we examined the insulin levels of mouse serum during the time-course of the experiment." (PMID 36424602, 2022). "The combination therapy reduced the levels of fasting blood glucose and plasma insulin and prevented obesity and inflammation." (PMID 36092861, 2022). "In this study, we show that mice feeding with HFD exhibit diet‐induced obesity and decreases in glucose homeostasis, insulin sensitivity, and energy expenditure rate." (PMID 36062491, 2022). "Obesity is accompanied by chronic inflammation in several tissues, which triggers adverse effects on insulin sensitivity." (PMID 35789435, 2022). "The role of UCP2 in insulin secretion has also been recently reviewed, describing studies linking UCP2 to obesity that focus on the inflammatory process associated with ROS." (PMID 35884932, 2022). "As increased density of airway sensory nerves is a feature of human asthma, our findings underscore the previously undefined role insulin plays in mediating obesity-related asthma and further reveal the cellular pathway and mechanism of insulin action." (PMID 36107629, 2022). "Accordingly, specific correlations between different eCBome players and markers of obesity as well as insulin and glucose homeostasis have been described." (PMID 35158670, 2022). "Islet O-GlcNAcylation is increased in early obesity and is required for β-cell adaptation to enhance insulin secretion in early states of obesity." (PMID 36387851, 2022). "In previous animal studies, two Parabacteroides species, including Parabacteroides distasonis and Parabacteroides goldsteinii, played roles in anti-obesity, hyperglycemia, and insulin resistant." (PMID 35832425, 2022). "Vanadium compounds are known to inhibit adipogenesis and, thus, many insulin mimetic agents can also be used to treat obesity." (PMID 35159385, 2022). "We also measured serum concentrations of tumor necrosis factor -α (TNFα), which has postulated roles in obesity and insulin action." (PMID 35198905, 2022). "In their adipocytes, resistin decreases glucose transport in response to insulin, proposing a connection between obesity and insulin resistance." (PMID 35627631, 2022). "Gallic acid was demonstrated to have anti-obesity properties by suppressing lipogenesis, improving insulin signaling, and reducing proinflammatory responses and oxidative stress." (PMID 36187008, 2022). "Individuals with obesity are also more likely to be insulin resistant and have chronic hyperinsulinemia." (PMID 35048536, 2022).
Obesity (continued). "Resistin is a polypeptide with a molecular weight of 12.5 kDa; it consists of 108 amino acids, its secretion is increased with obesity, and it acts directly on adipocytes, inhibiting insulin-induced glucose uptake." (PMID 36499312, 2022). "Being a well-recognized molecular link between obesity, declining insulin action, and eventually the development of T2DM, ER stress enacts in a complex way." (PMID 35370992, 2022). "Lower protein synthesis in muscle of humans with obesity is observed concomitantly with lower insulin sensitivity and higher HbA1c values." (PMID 35350688, 2022). "In obesity, insulin-mediated vasoconstriction via the activation of the ERK1/2 pathway becomes dominant, as its activation of the PI3K pathway in endothelial cells is selectively inhibited, consequently blocking downstream capillary recruitment." (PMID 35055038, 2022). "Patients unaware of their overweight and obesity presented significantly worse blood lipids, insulin resistance and blood pressure parameters than participants with normal weight." (PMID 36078874, 2022). "The combination of obesity and T2D were shown to exhibit higher serum insulin levels and BMA at the lumbar spine and femoral metaphysis compared to the subjects without T2D." (PMID 36187112, 2022). "This review aims to clarify the complicated interplay among Nrf2, oxidative stress, lipid metabolism, insulin signaling and chronic inflammation in obesity." (PMID 36290791, 2022). "In these studies, whole-body insulin clearance was reduced in people with obesity who were insulin resistant compared with both lean people and people with obesity who were insulin sensitive." (PMID 35054781, 2022). "PPARD agonists can promote cholesterol accumulation in macrophages, reduce obesity, increase fatty acid oxidation and oxidative phosphorylation in skeletal muscle, and increase insulin sensitivity." (PMID 36090166, 2022). "T2DM progression, often facilitated by obesity, typically begins with insulin resistance, where peripheral tissue insulin receptors become insensitive and require increased insulin to initiate a response." (PMID 36093092, 2022). "Adiponectin is an important target in obesity treatment, is a key regulator of fatty acid oxidation and lipid synthesis, and is well known to decrease triglyceride concentrations and increase insulin sensitivity." (PMID 36402758, 2022). "The authors also recommended against measuring insulin concentrations when evaluating children or adolescents for obesity." (PMID 36313105, 2022). "Early-onset obesity further dysregulated the pulmonary adipokine/insulin signaling pathway, leading to an asthma-like disease in adulthood." (PMID 36051916, 2022). "Although the relationship between obesity and adipose expression of ACE2 is debatable, the insulin-resistant and obese AT is associated with T-cell exhaustion due to programmed death-ligand 1 (PD-L1) overexpression, altered methylation of ACE2." (PMID 35211733, 2022). "On the contrary, a lower type I–to–type II ratio is related to decreased insulin sensitivity, observed in obesity, metabolic syndrome, and T2D." (PMID 36275635, 2022). "The regulation of β cell mass is essential for the compensatory response of the endocrine pancreas to situations of increased insulin demand such as obesity." (PMID 35198097, 2022). "The relationship between the signaling and actions of leptin and insulin is more evident in obesity, where skeletal muscle shows resistance to leptin actions, contributing to the accumulation of lipids including intramuscular long-chain fatty acyl-CoA." (PMID 35884769, 2022). "Among its functions, it has anti-inflammatory and vascular protective properties, as well as functions to combat obesity by stimulating fatty acid metabolism and tissue sensitivity to insulin." (PMID 36262532, 2022). "We found that fat body reduction of DHAPAT reduces DAGE and improves pathophysiology phenotypes, including obesity, glucose levels, cardiac function, and insulin signaling." (PMID 35906462, 2022).
Obesity (continued). "From a clinical perspective, circulating MSTN levels are elevated in individuals with obesity, and weight loss reduces MSTN levels and improves insulin sensitivity." (PMID 35740032, 2022). "The rapid absorption of glucose in the intestinal tract leads to excessive release of insulin and fat deposition, followed by a reduction in blood glucose concentration, resulting in repeated glucose uptake and eventually leading to obesity." (PMID 35456474, 2022). "A review covers RA actions in suppressing obesity, by opposing insulin action (promoting energy expenditure and inhibiting de novo lipogenesis) and inhibiting the differentiation of white preadipocytes into mature white adipocytes." (PMID 35458115, 2022). "CGRP is known to induce resistance to insulin and obesity by decreasing the release of insulin from β-cells." (PMID 35627115, 2022). "It was demonstrated that high-fat feeding and obesity induce ER stress in the liver, which suppresses insulin signaling via c-Jun N-terminal kinase activation." (PMID 36078578, 2022). "Higher concentrations of Leptin, insulin, and C-peptide are strongly associated with excessive GWG and obesity." (PMID 36224521, 2022). "L-Theanine, a nonprotein amino acid enriched in green tea, was recently found not only to significantly induce the beiging of subcutaneous WAT in mice, but also ameliorate obesity and improve glucose tolerance and insulin sensitivity in HFD-fed mice." (PMID 35216415, 2022). "In the literature, the Acetatifactor genus has been described to activate the bile acid membrane receptor TGR4 and, in this way, stimulate GLP-1 secretion, which improves obesity and, consequently, liver function and tolerance to insulin and glucose." (PMID 36558371, 2022). "Recent studies have shown that although obesity is a risk factor for adverse events, diminished abdominal fat may reduce obesity-related disorders, because less deposition of abdominal fat can increase insulin sensitivity, reduce cardiovascular risks, as well as achieve relatively benign prognosis." (PMID 36229850, 2022). "The protection against obesity in female mice has been attributed to the effects of circulating oestrogen levels on glucose and insulin homoeostasis, body fat distribution, pro-inflammatory markers, and hepatic lipogenesis." (PMID 35794191, 2022). "Consistent with our finding of altered mitochondria function, most human studies showed mitochondrial dysfunction in skeletal muscle from insulin-resistant offspring of patients with T2D, obesity, and T2D." (PMID 36876056, 2022). "We found that the presence of vanB in the baseline microbiota impacted the response to vancomycin treatment in gut microbial composition, AT insulin sensitivity and AT gene expression in men with overweight or obesity and impaired glucose metabolism." (PMID 35695620, 2022). "For the reason that GLP-1 increases insulin release from pancreatic β-cells in a glucose-dependent manner, incretins are important for the compensatory release of insulin in obesity." (PMID 36501131, 2022). "Short-chain fatty acids (SCFAs), produced by our gut microbes, have shown positive effects on preventing and counteracting obesity in the mechanism of energy homeostasis, lipid metabolism, and insulin sensitivity (15, –, 17)." (PMID 35293806, 2022). "Islet β cells play an important role in the development of obesity and diabetes by producing and storing large amounts of insulin, which is secreted precisely into the circulation when stimulated by glucose." (PMID 36092861, 2022). "Fecal microbiota transplantation from lean donors to patients with obesity and metabolic syndrome (MS) has shown significant improvement in insulin sensitivity after 6 weeks with FMT from a lean donor (allogeneic) vs. FMT autologous or aFMT." (PMID 36313072, 2022).
Obesity (continued). "In fact, in one study, both MHO and metabolically unhealthy obesity groups, characterised by the same body weight, displayed significant impaired insulin sensitivity compared with the reference control." (PMID 36142317, 2022). "Two SAT modules were predicted to be involved in regulating adipocyte differentiation and promoting obesity-related inflammatory responses to impair insulin signaling." (PMID 35603204, 2022). "Obesity also reduces insulin sensitivity, which is associated with higher exogenous insulin needs, chronic inflammation, and higher risk for hypoglycemia, dyslipidemia, and increased risk of long-term complications." (PMID 35873174, 2022). "Animal models used to investigate the relationship between obesity and insulin action often use a diet high in fat and high in simple carbohydrates (sucrose, fructose) to cause fat gain, insulin resistance, and hepatic steatosis." (PMID 36394259, 2022). "The ability to metabolize tauro-β-muricholic acid, a natural FXR antagonist, is essential for the microbiota to induce obesity and steatosis, as well as reduced glucose and insulin tolerance." (PMID 35628369, 2022). "For example, miR-17-5p and miR-519d are related to obesity and lipogenesis, miR-375 controls insulin secretion from the pancreas, whereas the let-7 family affect insulin sensitivity and regulate various players in glucose metabolism." (PMID 35054972, 2022). "ROCK2+/- mice on HFD demonstrated increased sensitivity to the browning effects of beta-adrenergic stimulation, increased energy expenditure with reduced obesity, and improved insulin sensitivity." (PMID 35769086, 2022). "Obesity leads to the dysregulation of insulin signaling, negatively impacting cellular signaling pathways and promoting cancer growth." (PMID 35326592, 2022). "TNFα is a crucial cytokine in neuroinflammation secondary to obesity, even critical in glucose metabolism by attenuating insulin signaling pathways and increasing levels of IL6, activating a neuroinflammatory state." (PMID 35422689, 2022). "Increased TNF with obesity impairs insulin signaling and contributes to insulin resistance and diabetes." (PMID 37990728, 2022). "On the other hand, transplantation of GPS2-overexpressing bone marrow into ob/ob and HFD-induced obesity mouse models reduced inflammation and improved insulin sensitivity." (PMID 36499659, 2022). "Because adiponectin can increase insulin sensitivity, it is also known to prevent obesity-related metabolic disorders, whereas low blood concentration of adiponectin is believed to be associated with DM and CVD." (PMID 36556970, 2022). "Nicotine can reduce obesity-related inflammation by restoring glucose homeostasis and insulin sensitivity, have an immunosuppressive effect, and reduce ROS release." (PMID 35893255, 2022). "In pregnancy complicated with obesity, the inflamed state of the adipose tissue directly feeds into earlier onset and higher levels, of insulin resistance, leading to earlier switch from lipogenesis to lipolysis during pregnancy." (PMID 35391836, 2022). "Hypotaurine decreased liver injury and fat accumulation in the NAFLD mice model, and hypotaurin supplementation was shown to increase insulin sensitivity in obese mice in an obesity model." (PMID 35399623, 2022). "Validated target genes of the miRNAs of interest, in relation to sarcopenia, obesity, and related conditions (e.g. insulin resistance, inflammation, and cachexia) where possible, were identified by conducting a literature search using PubMed." (PMID 34984856, 2022). "Subjects with prediabetes in cluster 2 represented an obesity-related insulin-resistant phenotype, in which participants also had hyperinsulinemia and a higher level of HOMA-IR and HOMA-β." (PMID 36072936, 2022). "Some studies have found that the relative abundance of Akkermansia was negatively correlated to obesity and that it helps improve obesity and insulin resistance." (PMID 36438869, 2022).